CLGN (calmegin)
Description:
Functions during spermatogenesis as a chaperone for a range of client proteins that are important for sperm adhesion onto the egg zona pellucida and for subsequent penetration of the zona pellucida. Required for normal sperm migration from the uterus into the oviduct. Required for normal male fertility. Binds calcium ions (By similarity).
Tractability: Antibody: UniProt predicts a signal peptide or a membrane-spanning region. PROTAC: ubiquitination databases record sites on it.
Gene: Protein-coding gene on chromosome 4 (140,387,952 to 140,427,661, reverse strand). Ensembl gene ENSG00000153132.
Subcellular location: Endoplasmic reticulum membrane
Subcellular location (Human Protein Atlas): Endoplasmic reticulum; Equatorial segment; Mid piece
Gene Ontology:
Molecular function: calcium ion binding; protein folding chaperone
Biological process: ERAD pathway; protein folding; single fertilization
Cellular component: endoplasmic reticulum; endoplasmic reticulum membrane; nuclear envelope
Genetic constraint (gnomAD): Loss-of-function variants: 32 observed, 51.96 expected, observed/expected ratio (o/e) 0.62, 90% interval 0.46 to 0.83. The upper end of that interval is the gene's LOEUF score, 0.83, which puts it in group 3 of 6, group 1 being the genes least tolerant of losing a copy. Missense variants: 469 observed, 547.51 expected, observed/expected ratio (o/e) 0.86, 90% interval 0.79 to 0.93. Synonymous variants: 178 observed, 177.65 expected, observed/expected ratio (o/e) 1, 90% interval 0.89 to 1.13.
Homologues: Orthologues: chimpanzee CLGN (99% identical), macaque CLGN (97% identical), dog CLGN (89% identical), pig CLGN (88% identical), rabbit CLGN (87% identical), rat Clgn (81% identical), mouse Clgn (80% identical), guinea pig CLGN (78% identical), zebrafish clgn (60% identical), tropical clawed frog clgn (59% identical), Drosophila melanogaster Cnx99A (45% identical), Caenorhabditis elegans cnx-1 (39% identical), and 1 more. Paralogues in human: CANX (56% identical), CALR (28% identical), CALR3 (19% identical).
Diseases named in the same sentence as CLGN in open-access papers:
CLGN is named in the same sentence as 23 diseases in open-access papers, as found by Europe PMC text mining. Sharing a sentence is not in itself a finding about the gene and the disease. The quoted sentences say what the papers report.
adenoma (4 papers, 2021 to 2024). A neoplasm arising from the epithelium. "CLGN, known as ER chaperone calmegin, is a highly expressed ER-associated gene in aldosterone-producing adenomas, but its role in diabetes remains unclear." (PMID 39553470, 2024). "A study revealed that CLGN was strongly expressed in aldosterone-producing adenomas and aldosterone-producing cell clusters." (PMID 36910333, 2023). "A recent study found that CLGN was up-regulated in aldogen-producing adenomas and was related to the generation of aldosterone." (PMID 36698420, 2022). "The endoplasmatic reticulum carrier Calmegin (CLGN) is also upregulated in APAs compared to non-functioning adenomas, with a clear positive correlation with CYP11B2 expression." (PMID 34771744, 2021).
breast carcinoma (3 papers, 2015 to 2022). "CLGN methylation has been associated with risk for prostate cancer and breast cancer." (PMID 36291758, 2022). "Calmegin (CLGN), a vital component for the membrane transport of target proteins, had been shown to be positively correlated with the progression of breast cancer." (PMID 36120545, 2022). "The over-expressed CCNE1, CLGN, NEK2, PTTG1 and RAD51, and the under-expressed ADAMTS1, FOS, FOSB, IL6 and ZFP36 in tumor cells are examples of breast cancer genes without differential promoter methylation between normal and tumor samples." (PMID 25706888, 2015).
Infertility (3 papers, 2020 to 2023). "It has been documented that calmegin is transcriptionally regulated by histone deacetylase and CpG methyltransferase; the deregulation of calmegin methylation capability may lead to infertility, endocrine-, prostatic- and germ cell neoplasms." (PMID 36765856, 2023). "In addition, we also noticed some genes which are related with Piétrain economical traits: MRAP2 can regulate the energy homeostasis machinery; CLGN, an important modulator in spermatogenesis and infertility." (PMID 32455573, 2020). "However, we observed several genes which were related to Piétrain specific economic traits around ROH regions, such as MRAP2 which was related to energy homeostasis machinery, and CLGN which was involved in the control of spermatogenesis and infertility." (PMID 32455573, 2020). "Therefore, CLGN may play an important role in spermatogenesis and infertility." (PMID 36698420, 2022).
hepatocellular carcinoma (2 papers, 2022 to 2025). A malignant tumor that arises from hepatocytes. "In summary, our study provides evidence supporting a model in which CLGN, upregulated by endoplasmic reticulum stress (ERS), contributes to hepatocellular carcinoma (HCC) progression and drug resistance, potentially via the NF-κB pathway." (PMID 41395613, 2025).
breast invasive carcinoma (1 paper, 2022). "In addition, the mRNA expression of CLGN was high in breast invasive carcinoma, kidney chromophobe, kidney renal papillary cell carcinoma, lung adenocarcinoma, lung squamous cell carcinoma prostate adenocarcinoma, and uterine corpus endometrial carcinoma (p < 0.01)." (PMID 36698420, 2022). "Additionally, CLGN was found to be significantly upregulated in invasive breast cancer, chromophobe renal cell carcinoma, papillary renal cell carcinoma lung adenocarcinoma, lung squamous cell carcinoma, prostate adenocarcinoma, and uterine corpus endometrial carcinoma." (PMID 36698420, 2022).
gastric cancer (1 paper, 2023). A primary or metastatic malignant neoplasm involving the stomach. "Separate analysis of patients with gastric cancer and non–small cell lung cancer showed that all 4 of the analytes (CLGN, TXD15, HSPA5, and RCN1) were significantly increased in patients who developed clots in both gastric and non–small cell cancer cohorts." (PMID 37651191, 2023).
non–small cell lung cancer (1 paper, 2023). A group of at least three distinct histological types of lung cancer, including non-small cell squamous cell carcinoma, adenocarcinoma, and large cell carcinoma. "CLGN (increased 4.2-fold) is a functional analog of calnexin that is typically expressed in testes but is upregulated in malignancies, including gastric and non–small cell lung cancer." (PMID 37651191, 2023).
sarcoma (1 paper, 2023). A usually aggressive malignant neoplasm of the soft tissue or bone. "In this study, we report the first case of BCOR-rearranged sarcoma with a novel CLGN fusion that shared morphological and immunophenotypical similarities with other more common fusion variants, which contribute to the continued expanding molecular subtypes of BRS." (PMID 36765856, 2023).
thyroid tumor (1 paper, 2009). A benign or malignant neoplasm affecting the thyroid gland. "The differential expression of the folding protein calmegin (CLGN) with FTA and FTC samples may be associated with a difference in the abundance of the protein, as recently described in thyroid tumors." (PMID 19893615, 2009).
varicocele (1 paper, 2020). A condition characterized by the dilated tortuous veins of the spermatic cord with a marked left-sided predominance. "Nonetheless, proteins, such as CLGN, FTH1, MDH1, MIF, PPP3CA, SUCLA2, and PSMA7, involved in sperm function, apoptosis, and oxidative stress were present in a low and very low abundance in the unilateral and bilateral varicocele group, respectively." (PMID 32365753, 2020).
tumor (5 papers, 2015 to 2025). "Higher pTNM stage, increased histological grade, and confirmed tumor presence were strongly associated with the high CLGN expression group." (PMID 41395613, 2025). "Among them, the promoter methylation level of CLGN was stronger in the tumor group, while the methylation levels of the other three genes were significantly reduced in the tumor group, especially PPP1R16A." (PMID 39010084, 2024). "The HPA database results also showed that CLGN protein levels were higher in HCC than in non-tumor tissues." (PMID 36698420, 2022). "The p rotein expression of CLGN in tumor and normal tissues of clinical specimens from patients with HCC was investigated." (PMID 36698420, 2022). "Intriguingly, Pae treatment also downregulated CLGN expression itself, implying that its anti-tumor effect may be mediated partly through suppressing the CLGN/NF-κB axis." (PMID 41395613, 2025). "Based on this, we hypothesized that CLGN might influence the progression of HCC by promoting cell proliferation or inhibiting tumor cell apoptosis, which requires further study in the future." (PMID 36698420, 2022). "However, a CLGN translocation/fusion-associated tumor, based on our best knowledge, has not been reported as yet." (PMID 36765856, 2023). "ERS significantly upregulated CLGN in HCC, correlating with advanced tumor stage and poor prognosis." (PMID 41395613, 2025). "Its expression correlated with tumor presence, age, sex, AFP level, and histological grade.To visualize the relationships between CLGN expression and clinicopathological features, a Sankey diagram was generated." (PMID 41395613, 2025).
cancer (2 papers, 2022 to 2023). A tumor composed of atypical neoplastic, often pleomorphic cells that invade other tissues. "CLGN is considered a testis-specific protein in the healthy host but is upregulated in cancer." (PMID 37651191, 2023). "However, the role of CLGN in several malignant tumors, including HCC, remains unclear." (PMID 36698420, 2022). "Some of these markers are ubiquitous among cells and cancer types (e.g., HSPA5), but others may be useful only for specific malignancies (e.g., CLGN)." (PMID 37651191, 2023). "HSPA5, RCN1, CLGN, and TXD15 need to be validated using an assay method compatible with use in a central lab (e.g., ELISA) in a large prospective study of patients with advanced-stage cancer before these proteins can be used to guide anticoagulation prophylaxis." (PMID 37651191, 2023).
CLGN also shares sentences with these, for which no sentence is quoted: diabetes (1 paper); germ cell neoplasms (1); kidney chromophobe (1); liver cancer (1); lung adenocarcinoma (1); lung squamous cell carcinoma (1); papillary renal cell carcinoma (1); prostate adenocarcinoma (1); prostate carcinoma (1); small cell carcinoma (1); uterine corpus endometrial carcinoma (1).